IL17A (interleukin 17A)
Diseases named in the same sentence as IL17A in open-access papers (continued):
Sharing a sentence is not in itself a finding about the gene and the disease.
synucleinopathy (1 paper, 2022). A neurodegenerative disease that is characterized by the abnormal accumulation of aggregates of alpha-synuclein protein in neurons, nerve fibers or glial cells. "This study also identified discrete populations of α-syn reactive CD4+ T cells that express CXCR4 and IL17A which were present in the cerebro-spinal fluid of synucleinopathy patients and are correlated to the neurodegenerative phenotype." (PMID 35897751, 2022).
Systemic Amyloidosis (1 paper, 2024). "In the present study, inhibition of IL-17A was significantly effective against systemic amyloidosis, whereas inhibition of IL-17F was not." (PMID 39519167, 2024).
tapeworm infections (1 paper, 2023). "This suggests that tapeworm infections could initiate the TGF-β/Smad signaling pathway, upregulate TβRI, TβRII, and Smad2/3, and in turn induce the host to secrete a large amount of IL-17A, thus stimulating predominantly Th17-mediated immune responses." (PMID 36985175, 2023).
temporomandibular joint disorder (1 paper, 2015). Any condition affecting the anatomic and functional characteristics of the temporomandibular joint. "Here, we investigated the roles of IL-17A in temporomandibular joint disorders (TMD) using genome-wide analysis of synovial fibroblasts isolated from patients with TMD." (PMID 26839464, 2015).
tick-borne encephalitis (1 paper, 2018). Tick-borne encephalitis is caused by an arbovirus of the Flaviviridae family (tick-borne encephalitis virus, TBEV), transmitted principally by the bite of the Ixodes ricinus tick. "Concentrations of IL-17A, IL-17F, IL-22, CXCL1, and CXCL2 in serum (S) samples obtained from tick-borne encephalitis patients on admission to hospital are shown horizontal axes and in cerebrospinal fluid (CSF) samples obtained simultaneously on vertical axes (expressed in pg/ml)." (PMID 29678185, 2018).
upper respiratory tract diseases (1 paper, 2022). "IL-17A secreted by these cells plays roles in both innate and acquired immunity and upper respiratory tract diseases." (PMID 35075349, 2022).
uterine disease (1 paper, 2015). "IL17A drives the recruitment of inflammatory cells (via increased expression of IL-8) as well as the proliferation of stromal cells which contributes to the pathogenesis of uterine disease in humans." (PMID 26482908, 2015).
uterine fibroids (1 paper, 2025). "In line with this, in uterine fibroids, the phagocytic ability of neutrophils is affected by the serum levels of IL-2, IL-17A, IL-6, and IL-4." (PMID 40943781, 2025).
Wegener’s granulomatosis (1 paper, 2015). "Percentages of IL-17A-producing activated T cells is increased in ANCA-positive Wegener’s granulomatosis patients." (PMID 25964886, 2015).
tumor (2,374 papers, 2007 to 2026). "Tumor-associated neutrophils (TANs) have been shown to produce interleukin IL-17a, which promotes epithelial–mesenchymal transition of GC cells via JAK2/STAT3 signaling." (PMID 40136652, 2025). "Overall survival analysis reinforced the essential role of CD8+ T cells in mediating tumour control in the IL17A‐deficient setting." (PMID 40831074, 2025). "The effects of IL-4, IL-13, and IL-17A on tumor immunity are controversial, as various studies have shown they are associated with tumor progression or tumor suppression." (PMID 39743545, 2025). "Depletion of these cells strongly impaired the effect of the ENO1‐DNA vaccine in limiting tumour growth and improving survival in IL17A‐deficient mice, while in IL17A+/+ mice, the role of CD4+ T cells was much more crucial." (PMID 40831074, 2025). "This is further supported by our spatial transcriptomics data, which revealed increased expression of immunoglobulin‐related genes in IL17A‐deficient, vaccinated tumours consistent with enhanced local B‐cell activity." (PMID 40831074, 2025). "While capable of effective cytotoxicity and IFN-γ production, certain Vδ1+ populations secrete IL-17A, a cytokine associated with angiogenesis, neutrophil recruitment, and the promotion of MDSCs, all of which contribute to tumor progression." (PMID 40746558, 2025). "This IL-17A bias is particularly significant, as IL-17A-mediated inflammation has been implicated in promoting tumor progression through the recruitment of protumor immune cells and the establishment of a chronic inflammatory milieu." (PMID 40746558, 2025). "Regarding systemic cytokines and tumor gene expression, high IL‐17A levels were significantly associated with HPV18 (p < 0.05)." (PMID 41263059, 2025). "On the other hand, tumours with a higher infiltration level of PD-L1+ lymphocytes in tumour islets or stroma were significantly associated with higher IL-17A+CD4+ T cell infiltration in tumour islets." (PMID 39409156, 2024). "Consistent with our data, however, the promotion of the related EMT and EMT‐associated biological processes by IL‐17A have been described for OC as well as other tumor entities." (PMID 38566518, 2024). "As our survival analyses indicate an association of both IL17A mRNA expression in tumor tissue and IL‐17RC levels in ascites with a short survival, the pro‐tumorigenic functions of IL‐17A appear to predominate in determining the clinical outcome." (PMID 38566518, 2024). "Further analysis of the subsets of CD4+ T cells showed that tumours with higher infiltration levels of PD-L1+ lymphocytes in tumour islets were significantly associated with higher IL-17A+CD4+ T cell infiltration in the same compartment." (PMID 39409156, 2024). "Numerous studies have demonstrated that IL-17A levels in the blood of cancer patients are associated with tumor stage." (PMID 39676857, 2024). "Patients facing higher rates of tumor-associated mortality also tend to exhibit higher levels of specific cytokines (e.g., IL-6, IL-17A, IL-22, and transforming growth factor-β (TGF-β))." (PMID 39267848, 2024). "A recent study revealed that C. albicans promoted OSCC development via the IL-17A/IL-17RA-macrophage axis, and the tumor-associated macrophages (TAMs) attracted by C. albicans infection polarized into the M2 phenotype with high expression of PD-L1." (PMID 38515216, 2024). "Th17 cells play a crucial role in inflammation and tumor immunity through the secretion of Th17-associated cytokines such as IL-17A, IL-21, IL-23, and TNF46." (PMID 38172124, 2024). "In vivo, suppression of the IL‐17A pathway is associated with decreased tumor growth, increased tumor cell apoptosis, decreased metastasis, and increased survival." (PMID 38491831, 2024). "The results showed that cancer patients had significantly higher concentrations of IL8 and IL17A than the control group, indicating a proinflammatory state associated with the tumour stage." (PMID 38398137, 2024).
tumor (continued). "Interleukin (IL)-17A has been reported to be up-regulated in serum and tumor of GC patients, but the precise mechanisms underlying its involvement in gastric tumorigenesis are yet to be established." (PMID 36125689, 2023). "Recently it has been shown that OSCC-derived EVs induce overactivation of the IL-17A-signaling pathway in tumor tissue, causing an inflammatory cytokine imbalance in the tumor microenvironment, and thus promote OSCC xenograft tumor growth." (PMID 37373022, 2023). "Previous studies have demonstrated that IL-17A plays an important role in tumour-associated inflammation and cancer development." (PMID 37211606, 2023). "The IL-17A that causes these inflammation-associated malignancies can be secreted by Th17 lymphocytes or by the tumor cells themselves." (PMID 37978543, 2023). "The tumor infiltration of IL-17A-producing γδ T cells was positively associated with advanced tumor stages of human CRC and with other clinicopathological features, including tumor size, lymphatic and vascular invasion, and lymph node metastasis." (PMID 36793708, 2023). "In this study, we observed significant association between IL-17 A expression and patients’ age > 45 years, even smaller tumor size (≤ 1 cm), and disease progression in the follow-up period." (PMID 37563607, 2023). "Tumor-associated macrophage accumulation was associated with IL-17A/IL-17RA signaling pathway during C. albicans infection." (PMID 37067414, 2023). "In this study, we observed significant association in between IL-17 A expression and patients’ age > 45 years, even smaller tumor size (≤ 1 cm) and disease progression in follow up period." (PMID 37563607, 2023). "Previous studies suggested that IL-17A can cause oxidative stress, which in turn has a two-sided role in tumor development." (PMID 37978543, 2023). "Recently, research has suggested that IL-17A-mediated neovascularization is inextricably linked with the IL-6/STAT3 pathway in animal tumor models." (PMID 36873773, 2023). "Sharp et al33 showed that advanced CRC stage was associated with elevated tumor levels of IL-17, whereas we found that higher IL-17A mRNA expression correlated to the early tumor stage." (PMID 36098359, 2022). "GC cells can secrete IL-17A to promote the transformation of normal fibroblasts (NF) into tumor-associated fibroblasts (CAF)." (PMID 36341377, 2022). "the IL17A deficient mice were more susceptible to developing lung melanoma, and Th17 cells promote the activation of tumor-specific CD8+ T cells." (PMID 35902909, 2022). "They analyzed Plet 1-deficient mice in the AOM/DSS model and found reduced tumor numbers and reduced expression of proliferation marker Ki67, suggesting IL-17A-induced Plet1 expression contributes to colon tumorigenesis and cell proliferation." (PMID 36135048, 2022). "Studies further showed that the forced expression of IL-17A in the lung promotes tumor proliferation through IL-6 and tumor-associated neutrophils and that IL-17A mediates resistance to therapeutic programmed cell death protein 1 (PD-1) blockade." (PMID 35883573, 2022). "Clinical studies have shown that IL-17A, the main effector of Type 17 T cells, is associated with tumor-infiltrating CD8+ T cells." (PMID 35459193, 2022). "The antitumor activity of Type 17 T cells and IL-17A was associated with increased CD8 + T cell tumor infiltration." (PMID 35459193, 2022). "Interleukin 17A (IL-17A), as a hallmark cytokine of Type 17 T cells, has antitumor effects depending on the tumor environment and tumor type." (PMID 35459193, 2022). "Tc17 cells (characterised by IL-17A, IL-17F, IL-21, IL-22 production and low levels of granzyme B) have been associated with both anti-tumour (esophageal SCC patients) and pro-tumour activity (HNSCC patients)." (PMID 35406451, 2022). "It seems that despite operating through the same receptor, IL-17A and IL-17F cause contradictory effects on tumor progression." (PMID 35884974, 2022).
tumor (continued). "A significant reduction in tumor growth was observed in IL-17A-deficient mice in heterotopic models of HCC." (PMID 35281021, 2022). "In the AOM/DSS-treated mice, a blockade of IL-17A by IL-17A antibody or a deficiency of IL-17A was linked to reduced tumor size and number." (PMID 36135048, 2022). "We assessed some of these subtypes and found that high FOXP3/CD3 ratios and high IL17A tumor levels were associated with worse outcomes." (PMID 33648463, 2021). "In the WT EGFR subgroup analysis, IL-17A rs8193036 T-allele carriers had higher risks of developing an advanced tumor stage (p = 0.016) and lymphatic invasion (p = 0.049)." (PMID 33802737, 2021). "Altogether, the findings suggest that IL‐17A and B7‐H2+ neutrophils are closely associated with GC tumor progression and poor patient prognosis." (PMID 34185422, 2021). "The low expression of IL17A caused by the Smad7 expression in tumor-infiltrating CD4(+) T cells enabled the TNF-α-mediated killing of cancer cells both in vitro and in vivo." (PMID 34059951, 2021). "Tumor-associated γδ T cells were noted to have primarily expression of RORγt and IL-17A while γδ T cells in the peripheral lymph nodes and spleens of tumor bearing mice had significantly decreased IL-17 and RORγt levels as was also the case with GF mice." (PMID 33375062, 2020). "In the ETBF-infection colitis-associated cancer model, IL-17A is crucial to tumor promotion and progression." (PMID 33126615, 2020). "IL-17a deficiency considerably reduced KI-67 expression in tumor samples from PM2.5-challenged mice, while being restored by IL-17a reinjection." (PMID 32554855, 2020). "More recently, a microbiome has also been found in the blood and tumor of cancer patients, and microbiota-induced IL-17A has also been implicated in the pathogenesis of colon cancer, breast, pancreatic and ovarian carcinomas, and multiple myeloma (MM)." (PMID 33244315, 2020). "IL17A-mediated induction of IL-6 and Granulocyte-colony stimulating factor (G-CSF) expression in the tumor cells has been shown to recruit tumor-associated neutrophils (Ly-6G+)." (PMID 31921642, 2019). "IL-6 level was well correlated with tumor stage and undetectable IL-17A was associated with extrahepatic metastasis." (PMID 30824840, 2019). "A further complication in the definition of the pro-tumor properties of IL17 comes from the IL17A polymorphism rs2275913 (G197A), with the AG and AA genotypes strongly associated to an increased CRC incidence." (PMID 31130953, 2019). "Higher expression of CCL20 and IL-17A together or respectively were significantly associated with higher T stage, N stage, M stage, overall stage, deep invasion, liver metastasis, larger tumor size, adenocarcinoma type, and CEA values." (PMID 31387598, 2019). "In our previous study of K-ras mutant LUAD concurrent with COPD-related airway inflammation, IL-17 deficient (il17a−/−) mice have lower tumor proliferation and vascular density." (PMID 32039025, 2019). "In a recent in vivo study, IL-17A produced by Th17 cells caused tumor growth by changing the behavior and gene-expression profile of non-metastatic tumor cells, thus indicating a pro-tumorigenic role for IL-17A." (PMID 31366131, 2019). "Il17a deficient (CCSPcre/K-rasG12D; Il17a−/−) conferred decreased tumor progression, angiogenesis, pro-inflammatory cytokines, and Gr1+ CD11b+ myeloid cell abundance." (PMID 31921642, 2019). "Although an opposing role of Th17 and IL17A responses in cancer development is becoming evident, accumulating data from mouse studies suggest that Th17 cells can cause more significant tumor regression compared with Th1 cells." (PMID 31921642, 2019). "Oncogenic-driven NSCLC models have predominantly shown a pro-tumorigenic role of IL17A responses, whereas IL17A regulation in a loss of tumor suppressor NSCLC model has been associated with an anti-tumorigenic function." (PMID 31921642, 2019).
tumor (continued). "To further understand how tumor mutations impact Th17/IL17A response, we review the role of this response in human tumors as well as the studies in K-ras vs. non-K-ras driven NSCLC." (PMID 31921642, 2019). "In human SCC, tumor infiltration of IL-17A-producing Vδ1+ and Vδ2+ T cells was associated with a negative prognosis, in contrast to a more favorable outcome associated with tumor-infiltrating IFNγ-producing γδ T cells." (PMID 30538697, 2018). "This pro-tumor outcome of some γδ T cell responses appears predominately a consequence of IL-17A production that is often associated with the up-regulation of proliferation pathways in cancerous lesions." (PMID 30538697, 2018). "Of the pro-inflammatory cytokines, IL-17A has recently been associated with the progression of various types of tumor and is considered to be an important target for cancer therapy because its inhibition reduces cancer progression in animal models." (PMID 29983876, 2018). "The cytokine IL-17A is associated with the progression of various cancers, but little is known about the molecular cross-talk between IL-17A and other tumor-promoting factors." (PMID 29983876, 2018). "In previous studies, high level of IL-17A within tumor was shown to associate with poor survival of several cancers; whereas some other studies reported opposite results." (PMID 29029520, 2017). "It is well established that interleukin-17A (IL-17A) has a remarkable role on the promotion of inflammation and tumor formation, and IL-17 has been implicated in the enhancement of immunosuppression of MDSCs, which consequently promotes tumor progression." (PMID 28002798, 2017). "This phenomenon suggests that the IL-17A signaling in tumor cell proliferation is tightly regulated; however, the molecular mechanisms underlying the tumor-specific proliferation induced by IL-17A are largely understudied." (PMID 28562353, 2017). "In an experimental CAC model, IL-17A deficient mice have been shown to exhibit significantly lower tumor numbers compared to WT mice." (PMID 28881574, 2017). "IL-17A and IL-23 cause the attraction of lamina propria myeloid cells (macrophages, granulocytes) to the tumor site which are the major source of IL-6 and TNF." (PMID 28881611, 2017). "Meta-analysis showed that high level of IL-17A within tumor was significantly associated with decreased DFS in solid tumors (HR = 1.70, 95% CI 1.17 to 2.46, P = 0.005); while significant heterogeneity was observed (I2= 78.9%; P = 0.000)." (PMID 29029520, 2017). "NF-κB was a crucial target of IL-17A signaling pathway in many types of cells and it had been reported to function as a tumor promoter in inflammation-associated cancer." (PMID 28035060, 2017). "This study will provide novel experimental evidence for the underlying mechanisms of IL-17A-mediated tumor protective immunity." (PMID 26942702, 2016). "Our data suggest that IL-10 is closely linked to tumor-associated CD4+ populations expressing either IFN-γ or IL-17A, whereas the presence of TGF-β appears to be of secondary importance." (PMID 27075020, 2016). "Tregs from IL-17A deficient Apc/Min+ mice were used to assess the effect of the tumor environment and functional thymus." (PMID 26146642, 2015). "We also showed that adoptively transferred IL-17A-deficient Apc/Min+ Tregs inhibited tumor growth, suggesting that IL-17A was critical to impair the tumor regression function of Apc/Min+ Tregs." (PMID 26146642, 2015). "Another cytokine, IL-21 coordinates colitis-associated tumorigenesis, leading to high IFN-γ and low IL-17A expression, which decreases tumor cell proliferation and increases tumor immunosurveillance." (PMID 25590298, 2015). "Treatment with endothelin-1 receptor dual antagonist decreased IL-17A levels and caused slower 4T1 tumor growth." (PMID 26783383, 2015). "Dual-function was required for Th17 cell-mediated tumor destruction because cells deficient in IFN-γ or IL-17A had impaired activity." (PMID 24987392, 2014).